CREG2 (cellular repressor of E1A stimulated genes 2)
Tractability: Antibody: UniProt places it where antibodies can reach, with high confidence; UniProt predicts a signal peptide or a membrane-spanning region; its Gene Ontology location is reachable by antibodies, with medium confidence.
Gene: Protein-coding gene on chromosome 2 (101,345,550 to 101,387,503, reverse strand). Ensembl gene ENSG00000175874.
Subcellular location: Secreted
Gene Ontology:
Cellular component: cytoplasm; endomembrane system; endoplasmic reticulum; extracellular region; Golgi apparatus
Genetic constraint (gnomAD): Loss-of-function variants: 21 observed, 20.02 expected, observed/expected ratio (o/e) 1.05, 90% interval 0.74 to 1.51. The synonymous counts are far from expectation, so gnomAD's model fits this gene poorly and the ratio says little. Missense variants: 333 observed, 285.18 expected, observed/expected ratio (o/e) 1.17, 90% interval 1.07 to 1.28. Synonymous variants: 159 observed, 114.26 expected, observed/expected ratio (o/e) 1.39, 90% interval 1.22 to 1.59.
Homologues: Orthologues: chimpanzee CREG2 (98% identical), macaque CREG2 (88% identical), dog CREG2 (85% identical), mouse Creg2 (83% identical), rat Creg2 (82% identical), pig CREG2 (81% identical), guinea pig CREG2 (70% identical), zebrafish creg2 (47% identical), tropical clawed frog creg2 (47% identical), Drosophila melanogaster CREG (18% identical). Paralogues in human: CREG1 (26% identical).
Diseases named in the same sentence as CREG2 in open-access papers:
CREG2 is named in the same sentence as 9 diseases in open-access papers, as found by Europe PMC text mining. Sharing a sentence is not in itself a finding about the gene and the disease. The quoted sentences say what the papers report.
esophageal squamous cell carcinoma (1 paper, 2025). Esophageal squamous cell carcinoma (ESCC) is a type of esophageal carcinoma (EC) that can affect any part of the esophagus, but is usually located in the upper or middle third. "Higher expression of CREG2 correlates with shorter survival times in esophageal squamous cell carcinoma." (PMID 40124684, 2025).
gastric cancer (1 paper, 2023). A primary or metastatic malignant neoplasm involving the stomach. "CREG2 (cellular repressor of E1A stimulated genes 2) is highly expressed in malignant gastric cancer tissues and is positively correlated with tumor clinical stage, tumor metastasis, and stages of tumor infiltration." (PMID 37641095, 2023).
lung adenocarcinoma (1 paper, 2025). A carcinoma that arises from the lung and is characterized by the presence of malignant glandular epithelial cells. "The CREG2 gene is implicated in Lung Adenocarcinoma (LUAD), where its high expression is linked to poor prognosis and advanced tumor stages." (PMID 41358202, 2025).
lung carcinoma (1 paper, 2025). "This analysis led to the discovery of a 3-gene signature—comprising PPP1R3G, CREG2, and LYPD3—that is characteristic of the resistant lung cancer cells." (PMID 41358202, 2025).
meningioma (1 paper, 2021). A generally slow growing tumor attached to the dura mater. "Another four genes (PNMA6A, TIGD1, PTEN, and SMO) were found to be altered in >10% of all WHO grade 1 meningiomas investigated, while the remaining CREG2, EEF1A1, and POLR2A genes were recurrently altered in a minority (<10%) of cases." (PMID 34868937, 2021). "Overall, WHO grade 1 meningiomas harbored numerous and heterogeneous genetic variants, which most frequently affected the NF2 (47%) gene and to a less extent the PNMA6A (22%), TIGD1 (16%), SMO (13%), PTEN (13%), CREG2 (9%), EEF1A1 (6%), POLR2A (6%), ARID1B (3%), and FAIM3 (3%) genes." (PMID 34868937, 2021).
cancer (3 papers, 2022 to 2025). A tumor composed of atypical neoplastic, often pleomorphic cells that invade other tissues. "CREG2, involved in cellular respiration and energy metabolism, has potential indirect effects on cancer development." (PMID 41358202, 2025). "CREG2 showed significant binding with TMZ, and considering its involvement in various cancers, it can serve as a target protein for TMZ." (PMID 36364024, 2022). "Although the roles of MYRF, CREG2, and NLRP10 in NSCLC have not been extensively studied, their involvement in other cancers has been documented." (PMID 40124684, 2025).
CREG2 also shares sentences with these, for which no sentence is quoted: tumor (3 papers); laryngeal carcinoma (1); type 2 diabetes (1).